LINC01020 (long independently transcribed non-coding RNA 1020)
Gene: Long non-coding RNA gene on chromosome 5 (4,987,789 to 5,070,314, forward strand). Ensembl gene ENSG00000215231.
Diseases named in the same sentence as LINC01020 in open-access papers:
LINC01020 is named in the same sentence as 1 disease in open-access papers, as found by Europe PMC text mining. Sharing a sentence is not in itself a finding about the gene and the disease. The quoted sentences say what the papers report.
kidney tumor (1 paper, 2024). "Until now, no studies have reported the role of ACSF2 or LINC01020, or their interaction, in ferroptosis or kidney tumor prognosis." (PMID 38534739, 2024).